CXCL10 (C-X-C motif chemokine ligand 10)
Diseases named in the same sentence as CXCL10 in open-access papers (continued):
Sharing a sentence is not in itself a finding about the gene and the disease.
liver disease (39 papers, 2007 to 2025). "Increased expressions of DPP-4 in serum and the liver have been reported in patients with HCV-related liver disease, and a higher concentration of truncated CXCL10 has been associated with failure to spontaneously clear acute HCV infection." (PMID 34604157, 2021). "We conclude that in people living with HIV and HBV, liver disease is associated with elevated intrahepatic mRNA for CXCL10 and CXCR3." (PMID 32898182, 2020). "CXCL10 rs1439490 (G-201A) polymorphism has been associated with liver disease in patients infected with hepatitis B virus." (PMID 28755163, 2017). "Furthermore, serum and intrahepatic CXCL10 levels in patients are positively associated with the severity of hepatitis C virus (HCV)-induced liver disease 15,22." (PMID 32641985, 2020). "Based on our statistical analysis, we were indeed able to identify distinct concentration ranges for CXCL9 and CXCL10 that correspond to varying liver disease severity as defined by CTP, MELD-Na, and MELD 3.0." (PMID 41373861, 2025). "While TNF alfa, IL-6, and IL-8 (CXCL8) are markers of the innate immune “storm” (neutrophil-related), CXCL9 and CXCL10 reflect the adaptive immune response (Th1/lymphocytic) as well as hemodynamic severity (portal hypertension)." (PMID 41373861, 2025). "In our study, CXCL9 and CXCL10 were associated with mortality and correlated with MELD scores, likely because they reflect the underlying severity of ALD and portal hypertension, whereas IL-6 and IL-8 mainly capture the superimposed acute inflammatory trigger." (PMID 41373861, 2025). "In parallel, the chemokine Cxcl10, which promotes macrophage M1 polarization and contributes to inflammatory progression in steatotic liver disease, was also downregulated." (PMID 41516073, 2025). "Disease annotations suggested three of the proteins are linked to different types of cancer (CDCP1, CCL3, ITGA11), whereas another two are related to liver diseases (CXCL10, HGF)." (PMID 36737481, 2023). "Cxcl10 plays a crucial role in recruiting immune cells during the liver infiltration process in liver diseases." (PMID 38130716, 2023). "Of the chemokines contributing to improved predictability of cirrhosis, CXCL10, CCL3, and CCL4 have been implicated in progression of liver disease." (PMID 36358697, 2022). "C-X-C motif chemokine ligand 10 (CXCL10) plays an important role in hepatic disease." (PMID 36911674, 2023). "Being present in various inflammatory liver diseases, CXCL10 could be an important therapeutic agent." (PMID 37108648, 2023). "Previous clinical studies have also indicated that CXCL10 may play a pathogenic role in NASH and hepatitis C virus (HCV)-induced liver disease 15,22,58." (PMID 32641985, 2020). "We analyzed the association between changes in plasma biomarkers and liver disease severity scores (LSM and HVPG) during the follow-up, but we only found a positive association (p-value <0.05) between plasma variations of PD1, IL10, CXCL10, CCL2, and CXCL8 and the change in LSM values." (PMID 34497613, 2021). "Anti-CXCL10 may have a therapeutic potential for treatment of these liver diseases." (PMID 32641985, 2020). "CXCL10 was one of several CXC chemokines upregulated in liver tissue, correlating with the degree of neutrophil infiltration and portal hypertension." (PMID 41373861, 2025). "Patients with advanced liver disease, classified as MELD-Na ≥ 20, MELD3.0 > 19, and CTP class C, as well as poor short-term outcomes, presented with significantly higher CXCL9 and CXCL10 levels compared to their counterparts." (PMID 41373861, 2025). "In contrast, high CXCL10/IP-10 and CXCL9/Mig levels during HBV infection were correlated with severe liver disease." (PMID 36366543, 2022). "During chronic infection, serum and intrahepatic levels of CXCL10 were elevated and correlated with HBV DNA and alanine aminotransferase (ALT) enzyme levels, coupled with progressive liver disease." (PMID 36366543, 2022).
liver disease (continued). "We found a decrease in plasma biomarkers (PD1, PDL1, CXCL10, CXCL8, IL12p70, IL10, and TGFβ) and liver disease markers (stiffness measurement (LSM), hepatic venous pressure gradient (HVPG), and transaminases, among others)." (PMID 34497613, 2021). "Our data show an improvement in these immune and liver disease biomarkers in plasma (immune exhaustion (PD1), chemokines (CXCL10, CCL2, and CXCL8), and cytokines (IL10)) after achieving SVR with DAA therapy in HIV/HCV-coinfected individuals." (PMID 34497613, 2021). "Expression of interferon (IFN)-γ-inducible protein 10 (IP-10), also called C-X-C motif chemokine 10 (CXCL10), has been correlated with severity of injury in liver disease including viral hepatitis." (PMID 32898182, 2020). "A transcriptomic analysis identified CXCL10 as a distinct, upregulated chemokine in livers of patients with AH but not in other liver diseases." (PMID 41373861, 2025). "HBV-active ART will reduce this cycle through inhibition of both HIV and HBV replication, however given CXCL10 remains elevated on ART, this pathway may also be important in driving liver disease on treatment and requires further investigation." (PMID 32898182, 2020). "Interestingly, in patients with chronic liver disease, serum CXCL10 levels, but not hepatic CXCL10 mRNA levels, were positively correlated with portal hypertension, fibrosis stage, and disease progression." (PMID 31752395, 2019). "Besides, increased CXCL10 levels have been associated with liver injury in HCV-infected patients, and CXCL11 expression levels have been related to both portal and lobular inflammation; a clear relationship with liver disease in CHC has not been found." (PMID 28755163, 2017).
hepatitis C (36 papers, 2009 to 2026). "Interferon-related chemokines, particularly C-X-C motif chemokine ligand 10 (CXCL10/IP-10), are elevated in hepatitis C-associated mixed cryoglobulinemia." (PMID 41596381, 2026). "High CXCL10 levels have been associated with weaker responses to therapy in hepatitis C virus infection, while, in contrast, higher CXCL10 levels correlated with more pronounced declines of HBsAg during polymerase inhibitor therapies in hepatitis B and also PEG-IFNα-based HBV treatment." (PMID 25072849, 2014). "For example, previous studies have shown that the expression of IFN-γ and IFN-γ-inducible chemokines CXCL10, -9, -11 in hepatocytes and lymphocytes of hepatitis C patients increased, which was related to the degree of inflammation." (PMID 39605886, 2024). "In the context of hepatitis C virus infection, CXCL10 was suggested to contribute to persistent liver inflammation and fibrosis." (PMID 29062282, 2017). "The high CXCL10 level is higher in patients who develop thyroid disease, especially hypothyroidism in the setting of hepatitis C. It is possible that the endo-, exo-genous interferon and CXCL 10 combine to modify the immune response." (PMID 19954547, 2009). "Whether the down-regulation of CXCL10 by Candida favors the fungal infection as suggested in hepatitis C or Leishmaniosis needs to be explored." (PMID 40181464, 2025). "This means that CXCL10 may be involved in the antiviral response of patients with hepatitis C. Our results have also shown that CXCL10 exerted an inhibitory effect on HCV replication." (PMID 34345210, 2021). "Interestingly, CXCL10 levels correlate with severe liver damage levels in hepatitis-C infected patients." (PMID 24740099, 2014). "Increased CXCL10 and CXCR3 gene expression in chronic hepatitis B and hepatitis C patients were reported to correlate with the severity of the disease." (PMID 35307625, 2022). "In addition, the six upregulated DETGs are involved in Hepatitis C, including CDKN1A, TRAF3, CXCL10, CASP3, EIF2S1, and IFIT1." (PMID 37107704, 2023). "In hepatitis C the CXC-chemokine receptor CXCR3 and its ligands (CXCL9, CXCL10, CXCL11) have gained specific attention because various studies demonstrated elevated levels of CXCR3 ligand CXCL10 to be predictive of the failure to response to HCV therapy and to be associated with stage of fibrosis." (PMID 22792160, 2012).
glioblastoma (35 papers, 2010 to 2026). The most malignant astrocytic tumor (WHO grade IV). "Similarly, Cxcl10 has been associated with glioblastoma progression by enhancing immune cell recruitment and supporting a pro-tumorigenic microenvironment." (PMID 41282050, 2025). "Corroborating our findings, three key pro-inflammatory cytokines with known anti-tumoural functions (IL-6, CCL5 and CXCL10) are also significantly secreted by ZIKV-infected glioblastoma cells." (PMID 40240536, 2025). "Futureresearch should focus on CXCL10-targeting approaches in highly immunosuppressive tumors, such as pancreatic and glioblastoma, where immune checkpoint inhibitors have shown limited efficacy." (PMID 40760734, 2025). "These in vivo results corroborate our in vitro findings, demonstrating calycosin’s critical role in suppressing glioblastoma growth through CXCL10 inhibition." (PMID 38461458, 2024). "This study explores CXCL10 as a potential therapeutic target for calycosin in the suppression of glioblastoma." (PMID 38461458, 2024). "It has been well documented that blocking NF-kB decreases CXCR3 expression and CXCL10 in an autocrine feedback loop, thereby reducing glioblastoma cell proliferation." (PMID 38104126, 2023). "We identified a six gene cytokine-related signature (CCL2, CCR2, CXCL10, IL10RB, IL17B, and IL17R) capable of dividing glioblastoma patients into a low risk score group with favorable survival and a high risk score group with poor survival." (PMID 25978454, 2015). "Cxcl10 is reported to be a negative regulator of cell growth in glioblastoma." (PMID 35572197, 2022). "In intracranial U87 xenografts, immunostaining revealed that bevacizumab-resistant glioblastoma showed an increased amount of TAMs and increased M2/M1 ratio, defined by M2 markers (Arg-1, TGF-β, MMP9) and M1 markers (NOS2, CXCL10, IL-1β), compared to bevacizumab-sensitive glioblastoma." (PMID 34209679, 2021). "In this study, we found that calycosin inhibited glioblastoma growth by downregulating the CXCL10 signaling pathway in a subcutaneous GBM model, consistent with our in vitro findings." (PMID 38461458, 2024). "used high‐throughput tissue microarrays to detect CXCR3 and CXCL10 immuno‐expression in glioblastoma multiforme (GBM) and diffuse astrocytoma (DA) tissues." (PMID 35702353, 2022). "Maru S. have shown that stimulation by IP-10 (CXCL10) enhances ERK1/2 activation, promoting the proliferation of glioblastoma multiforme cells." (PMID 40733274, 2025). "RT-treated patients with low ARID1A expression from other tumor entities, such as skin cutaneous melanoma (SKCM), thyroid carcinoma (THCA), and glioblastoma multiforme (GBM), displayed higher expression of CXCL10, IL-6 and CXCL9." (PMID 38587186, 2024). "When previously explored in multiple glioblastoma cell lines, pIC was shown to modestly induce IFNβ expression but significantly induced ISG (ISG15 and CXCL10) expression in some of these cultures." (PMID 35603190, 2022). "In the present study, we surveyed and demonstrated the potency of the chemokines CXCL10, CCL2 and CCL11 to attract neoplastic glioblastoma cells in vitro and in vivo." (PMID 34830041, 2021). "The first experiment evaluated the chemoattraction potential of the chemoattractants CXCL10, CCL2, CCL11 individually and in combination on two established glioblastoma cell lines: F98 and U87MG." (PMID 34830041, 2021). "In previous research on glioblastoma, Qun Chen and colleagues found that EMP3 promotes the migration and M2 polarization of monocyte-derived macrophages and downregulates the production of chemokines induced by interferon, CXCL9 and CXCL10, by macrophages." (PMID 41000385, 2025). "There, genes with a higher expression in glioblastoma compared to astrocytoma were VEGFA, 4EBP1, CCL2, PLAU (uPA), CXCL8 (IL8), CXCL10 (IP10), CASP8, HGF, LIF, CD40, CDCp1, TNFRSF11B (OPG), CD274 (PD-L1), IL6, CXCL1, CCL20 (MIP3α), CCL8 (MCP2), CD244, MMP1, TNFRSF9, CXCL6, MMP10, FGF5)." (PMID 35301393, 2022).
glioblastoma (continued). "They showed an increased production of CXCL10, which induced an ERK1/2-dependent increase and DNA synthesis, suggesting that expression of CXCL10/CXCR3 axis have an important role in the proliferation of grade III astrocytoma and grade IV glioblastoma cells." (PMID 35269652, 2022). "Indeed, molecular analyses revealed enhanced expression of chemo-attractants (i.e., CXCL10, CCL4, and CCL3L1) and presence of T cells in the tumor when compared with a historical group of glioblastoma samples." (PMID 32235752, 2020). "We demonstrated that these glioblastoma cells were put into relatively cytokine "rich" environment produced by AT-MSC containing IL-1β, IL-1ra, IL-2, IL-4, IL-6, IL-8, TNF-α, IFN-γ, CCL5, CCL26, CXCL10, PDGF-bb." (PMID 20509882, 2010). "These could act in paracrine fashion alone or in combination to suppress glioblastoma cell growth such as described for synergistic inhibitory effect of TNF-α and IP-10 (CXCL10)." (PMID 20509882, 2010). "Furthermore, survival was longer in the Il-6 knockout mice relative to wild-type mice, which was not the case when SB28 glioblastoma was implanted into C57BL/6J Ccl2 or Cxcl10 knockout mice." (PMID 40161763, 2025). "In contrast, glioblastoma tumour cells may be the main source of CCL2, CXCL10 and CXCL12 production in the tumour microenvironment given the elevated CCL2 detected in GNS cell culture supernatants and the minimal levels of CXCL10 and CXCL12 detected in dissociated tumour supernatants." (PMID 35464424, 2022).
cervical carcinoma (34 papers, 2007 to 2025). A carcinoma arising from either the exocervical squamous epithelium or the endocervical glandular epithelium. "This study revealed that knockdown of PRMT5 in cervical cancer cells resulted in elevated CXCL10 expression, which was associated with a higher accumulation of CD8+ T cells in the surrounding tumor microenvironment." (PMID 41463372, 2025). "Higher expression of downstream STING pathway genes (e.g., CCL5, CXCL10) is associated with better survival in cervical cancer patients." (PMID 40539072, 2025). "It has also been found that CXCL10 causes the avoidance of the S phase of the cell cycle in cervical cancer cells, during which time the cells are least sensitive to radiation." (PMID 26622567, 2015). "Previous data have demonstrated that the CXC chemokine ligand 10 (CXCL10) inhibits angiogenesis, induces apoptosis and causes avoidance of the S phase of the cell cycle in cervical cancer cells." (PMID 26622567, 2015). "Notably, we uncovered a compelling association between CCL5, CXCL9, and CXCL10 and key prognostic factors, encompassing overall survival and progression-free survival, in cervical cancer, as observed within TCGA dataset." (PMID 38550593, 2024). "It is further validation of that CXCL10 is a diagnostic biomarker of cervical cancer." (PMID 36207693, 2022). "Liposome-encapsulated plasmid-encoding CXCL10 may inhibit the growth of cervical carcinoma by modulating the expression of E6 and E7 oncoproteins, induction of apoptosis and angiogenesis inhibition." (PMID 32455616, 2020). "In summary, these findings elucidate a novel mechanism whereby PRMT5 depletion in cervical cancer cells triggers a CXCL10-mediated chemotactic response, enhancing CD8+ T cell infiltration and restricting tumor progression." (PMID 41463372, 2025). "As revealed by this study, the antitumor effect in cervical cancer cells is linked to the silencing of PRMT5, which promotes T cell recruitment and regulates CXCL10 expression." (PMID 41463372, 2025). "We employed RT-PCR to ascertain the mRNA expression levels of CXCL8 and CXCL10 in human cell lines derived from cervical cancer." (PMID 38275602, 2024). "Our study further validates previous findings that CXCL8 and CXCL10 expression is elevated in cervical cancer." (PMID 38532933, 2024). "In another example, the HeLa cervical cancer cell xenograft model showed a synergistic effect when CXCL10 gene therapy and radiotherapy were combined." (PMID 37048082, 2023). "Chen and colleagues have demonstrated, in other HPV-driven cancers, specifically HPV-positive cervical cancer, that CXCL10 is upregulated and its receptor CXCR3 is overexpressed." (PMID 37686653, 2023). "CXCL10 was previously reported to promote tumoral PD-L1 expression in cervical cancer and gastric cancer." (PMID 37156839, 2023). "The combined markers displayed significant improvement for AUCs than individual SCC-Ag or CXCL10 in the analysis groups (healthy vs cervical cancer early stage, healthy vs all CESC." (PMID 36207693, 2022). "It is necessary to enlarge the sample size and analyze the changes of serum CXCL10 levels before and after surgery to further explore the clinical value of CXCL10 in the curative efficacy of cervical cancer." (PMID 36207693, 2022). "In conclusion, this study indicated that CXCL10 was a potential serum biomarker as a supplement to SCC-Ag in diagnosing cervical cancer." (PMID 36207693, 2022). "The diagnostic ability of CXCL10 for SCC-Ag-negative CESC patients was evaluated to explore the complementary role of CXCL10 for SCC-Ag in the diagnosis of cervical cancer." (PMID 36207693, 2022). "The results indicate that HPV infection can induce cervical cancer cells to secrete CXCL10, which binds to CXCR3 in the surrounding fibroblast cells,leading to JAK-STAT pathway activation and the subsequent upregulated expression of exosomal PD-L1." (PMID 34422627, 2021).